FLJ36000 (uncharacterized FLJ36000 )
Gene: Long non-coding RNA gene on chromosome 17 (22,381,747 to 22,458,385, forward strand). Ensembl gene ENSG00000276399.
Diseases named in the same sentence as FLJ36000 in open-access papers:
FLJ36000 is named in the same sentence as 1 disease in open-access papers, as found by Europe PMC text mining. Sharing a sentence is not in itself a finding about the gene and the disease.
FLJ36000 shares sentences with these, for which no sentence is quoted: lung adenocarcinoma (1 paper).